MRFAP1 (Morf4 family associated protein 1)
Synonyms: PAM14; PGR1
Tractability: PROTAC: ubiquitination databases record sites on it; its protein half-life has been measured.
Gene: Protein-coding gene on chromosome 4 (6,640,091 to 6,642,729, forward strand). Ensembl gene ENSG00000179010.
Subcellular location: Nucleus; Cytoplasm, perinuclear region
Subcellular location (Human Protein Atlas): Nucleoplasm
Gene Ontology:
Molecular function: protein binding
Cellular component: nucleoplasm; nucleus; perinuclear region of cytoplasm
Genetic constraint (gnomAD): Loss-of-function variants: 1 observed, 9.48 expected, observed/expected ratio (o/e) 0.11, 90% interval 0.037 to 0.5. That is too few expected variants to judge how well the gene tolerates losing a copy. Missense variants: 180 observed, 189.43 expected, observed/expected ratio (o/e) 0.95, 90% interval 0.84 to 1.08. Synonymous variants: 101 observed, 87.19 expected, observed/expected ratio (o/e) 1.16, 90% interval 0.99 to 1.37.
Homologues: Orthologues: macaque MRFAP1 (100% identical), mouse Mrfap1 (84% identical). Paralogues in human: MRFAP1L1 (85% identical), MRFAP1L2 (40% identical).
Diseases named in the same sentence as MRFAP1 in open-access papers:
MRFAP1 is named in the same sentence as 4 diseases in open-access papers, as found by Europe PMC text mining. Sharing a sentence is not in itself a finding about the gene and the disease. The quoted sentences say what the papers report.
tumor (1 paper, 2022). "Another promising tumor suppressor was described in the study by Hu and collaborators, with the knockout of the Morf4-family-associated protein 1 (MRFAP1) gene using CRISPR/Cas9 from the CG human cell lines." (PMID 36360266, 2022).
MRFAP1 also shares sentences with these, for which no sentence is quoted: cancer (1 paper); malaria (1); myopia (1).